MUC5AC (mucin 5AC, oligomeric mucus/gel-forming)
Diseases named in the same sentence as MUC5AC in open-access papers (continued):
Sharing a sentence is not in itself a finding about the gene and the disease.
infection (continued). "RSV lacks this sialic-acid cleaving capacity and host cells respond to infection by expression of mucins, the specific mucin protein MUC5AC is elevated in A549 human alveolar epithelial and bronchial epithelial cells." (PMID 29552008, 2018). "We observed enhanced expression of MUC5AC following infection in both 3-D models relative to uninfected controls, although no clear differences in mucus production between individual pathovars was observed." (PMID 28649632, 2017). "Curcumin treatment after NTHi infection also inhibited MUC5AC expression in a mouse model of OM, suggesting the clinical relevance of our findings." (PMID 28487811, 2017). "For example, Clca3, a putative calcium-activated chloride channel involved in the regulation of mucus production and/or secretion, and Muc5ac were upregulated after CK/1180 infection but downregulated after CK/1180-1214HA infection." (PMID 28100622, 2017). "In DMSO-treated serum-starved H292 cells, A2-2-20GF infection resulted in higher MUC5AC mRNA levels than mock, A2, and A2-2-20F infection." (PMID 27152417, 2016). "After treatment of the mice (starting at week 11 of infection), mRNA for Muc5ac returned to baseline levels." (PMID 25398130, 2014). "Increased production of Muc5ac has recently been shown to protect from severe infection with influenza virus." (PMID 25398130, 2014). "High levels of isolated production of Muc5ac in the lung, as found in Muc5ac-transgenic mice, protects from infection with influenza A virus." (PMID 25398130, 2014). "Intranasal infection of mice with the wild type strain of P. aeruginosa (PAK) for 24 hours induced a 3-fold increase in the amount of pulmonary muc5ac mRNA in WT mice as compared to PBS-treated mice." (PMID 22768318, 2012). "Infection of these cells with PAK led to an increased MUC5AC expression both at mRNA and protein levels." (PMID 22768318, 2012). "The expression of Muc5ac was modestly induced after hMPV infection in WT mice when compared to WT mock- infected mice." (PMID 22606349, 2012). "Immunofluorescence microscopy and immunohistochemistry confirmed the expression of Muc5ac after infection (days 15 and 21) in the cecal crypts of the resistant models." (PMID 20138044, 2010). "Unexpectedly, Muc5ac expression was also significantly up-regulated in the WT mice on days 14 and 21 after infection." (PMID 20138044, 2010). "However, all infections induced a significant reduction in Muc5ac detection compared to the mock epithelium." (PMID 40733536, 2025). "RV-A1 induced MUC5AC mRNA expression at 24 h post-infection." (PMID 39538325, 2024). "The induction of mucus secretion associated to mild infection by Pneumocystis has been described as part of a STAT6/FoxA2 pathway immune response, leading to the increment of the levels of the two most relevant mucins of the airways: Muc5ac and Muc5b." (PMID 37108906, 2023). "Furthermore, acute RSV infection increased expression of mucin genes Muc5b and Muc5ac in the lung, suggesting enhanced mucus production and goblet cell hyperplasia with infection." (PMID 37795093, 2023). "These correlations also held true for TSPAN8+ACE2+ and TSPAN8+MUC5AC− cells prior to infection." (PMID 36827975, 2023). "Deletion of muc5ac in mice does not cause pulmonary problems in rodents, but deletion of muc5b was shown to have severe, negative consequences regarding infection control and MCC." (PMID 36675209, 2023). "The pattern of expression of airway surface liquid (ASL) homeostasis-associated genes (CFTR, BPIFA1, MUC1, MUC5AC, MUC5B) in the PCLS varied greatly between the three strains, and only infection with strain T15 induced statistically significant changes in this group of genes." (PMID 38276150, 2023). "The two muc5 genes, muc5ac and muc5b, play an essential role in airway defence in human and mouse, particularly in producing mucin glycoproteins that protect the respiratory surfaces from infections." (PMID 36582361, 2022).
infection (continued). "However, the constancy of the MUC5AC to MUC5B ratio during infection, coupled with the absolute increases in MUC5B, indicated that RV induced both MUC5AC and MUC5B expression." (PMID 35239513, 2022). "Moreover, since the mucosal barrier plays a critical role in the innate immune system of the lung, we analyzed the influence of infection on the major secreted mucin, MUC5AC." (PMID 35558099, 2022). "Although MUC5B and MUC5AC play major innate immunity roles against ear infection, excessive induction of these mucins will lead to clogging of inner ear compartments, creating a niche for long term colonization and infection by microbial pathogens." (PMID 34180343, 2021). "Muc5AC stimulates anti-inflammatory TGFβ and produces mucin-5AC10, a gel-forming glycoprotein responsible for mucosal protection from infection and chemical damage, suggesting that airway colonization by microbiota in the HNM group induce a higher degree of inflammation." (PMID 32999331, 2020). "Another interesting observation made by an experimental study was that MUC5AC production is up-regulated in the acute, early phase of the infection, and this could promote the gastric colonization by H. pylori." (PMID 33322136, 2020). "Of interest, secreted MUC5AC increased later in the infection course." (PMID 30765827, 2019). "However, we found that the expression of CXCL8, MMP3, and MUC5AC was higher in the MG-infection group compared to the E. coli-infection group." (PMID 31803158, 2019). "In addition, an increase in goblet cells with reduction in Clara cells expressing CCSP that switch to coexpress CCSP and Muc5ac, has also been described in rodents during infection by Sendai Virus or Respiratory Syncytial Virus (RSV)." (PMID 31170201, 2019). "Diminished IL-13 expression at this stage of infection correlated with diminished Muc5ac expression and a defect in worm clearance, while application of recombinant IL-13 or transfer of CD4+ T cells from infected WT mice was sufficient to restore worm clearance." (PMID 29045902, 2017). "Tracheal mRNA levels of Muc5ac and Muc2 were significantly increased 12 hours after infection in mCLCA3-deficient mice and wild-type mice compared to PBS controls, whereas 24 hours after infection only Muc5ac was slightly elevated in the trachea of infected animals." (PMID 25033194, 2014). "To gauge the role of Muc5ac, we treated Mx1-deficient mice that were infected S. mansoni 10 weeks previously with Etanercept or PBS 3 and 1 day before, and also 1 and 3 days after infection with influenza A virus strain PR8 (2000 pfu/mouse)." (PMID 25398130, 2014). "In contrast, under similar conditions, infection of mice with the flagellin-deficient mutant (ΔFliC) did not lead to a significant increase in muc5ac expression." (PMID 22768318, 2012). "Importantly, mucin MUC5AC was significantly upregulated following BpWT infection." (PMID 40757824, 2025). "Indeed, staining for cell type-specific markers revealed an expansion of GSII+ mucous gland base cells upon infection, as well as an expansion of the proliferative compartment, overall leading to gland hyperplasia, whereas Muc5ac+ cells were relatively underrepresented." (PMID 35332152, 2022). "Although mucins MUC7 and MUC5AC were strongly downregulated in response to infection, consistent with our results at baseline, we found little evidence in this study for dysregulation of mucins (hypothesized to lead to loss of epithelial barrier function) being associated with scarring progression." (PMID 31964744, 2020). "MUC5AC production and deposition of Lewis determinants, especially LeX were upregulated in the milieu of live H. pylori as well as GE, CagA, UreA or LPS in vitro and in vivo during infection, more effectively in the acute (7 days) than in the chronic (28 days) phase of infection." (PMID 30841890, 2019).
infection (continued). "Interestingly, Muc5AC, which is associated with RSV infection, showed a significantly higher expression of mRNA in r19F-infected cells as compared with r19FCX4C at day four post infection." (PMID 31330970, 2019). "What might be the role of the infection-induced mucin Muc5ac in protection against the worms?" (PMID 20138044, 2010). "Validation by RT-qPCR confirmed significant upregulation of B3GNT6 and MUC5AC genes and downregulation of the SPRR gene family following BpWT infection." (PMID 40757824, 2025). "Results showed that MUC5AC, FGB, and CLDN18 were highly expressed only in the control group and L3 infection group, while CCL19 exhibited higher expression levels in the infection groups." (PMID 40979361, 2025). "We observed a similar induction of MUC5AC above baseline in patients with COPD on day 3 and an increase in concentrations of MUC5AC in patients with COPD versus healthy individuals on days 3 and 9 after infection." (PMID 35239513, 2022). "To confirm these findings, we additionally measured MUC5AC concentrations in an alternative sample type, bronchoalveolar lavage (BAL), as participants in the experimental infection study also underwent bronchoscopy at baseline and on day 7 after RV infection." (PMID 35239513, 2022). "MUC5AC concentrations were increased in patients with COPD versus those in healthy controls on days 3, 9, and 12 after infection." (PMID 35239513, 2022). "In this study, infection of the GC-treated in vitro lung model revealed reduced mucus production (MUC 1 and MUC5AC) as well as suppressed ciliary bead frequencies." (PMID 33803702, 2021). "MUC5AC is mainly produced in the epithelial goblet cells and was previously reported to slightly decrease in A549 cells under the influence of an RSV-infection after 48h." (PMID 31698728, 2019). "To examine the pHAECs response to infection by the two viruses, we determined the mRNA levels for RSV M as well as those of IL-6, CX3CL1, CCL7 (MCP-3), Muc5AC, and Muc5B." (PMID 31330970, 2019). "Here, we show that infection with helminths in the intestine also induces an ILC2-driven, IL-13–dependent goblet cell hyperplasia and increased production of mucins (Muc5b and Muc5ac) at distal sites, including the lungs and other mucosal barrier sites." (PMID 31582416, 2019). "IECs have been shown to differentiate into goblet cells following infection with T. muris in response to TH2 cell-derived cytokines and produce effector molecules such as the mucins Muc5AC and Muc2, cytokines such as TSLP as well as the small protein RELMβ." (PMID 27598373, 2016). "RV-infected Tbet-/- mice had high levels of MUC5AC in BAL and large amounts of PAS staining in the airway epithelium 7 days after infection." (PMID 27683080, 2016). "14C11 pre-treatment of RV-OVA challenged mice significantly reduced the induction of both MUC5AC and MUC5B mucus proteins 6 days after infection." (PMID 23935498, 2013). "H. pylori binds directly to purified MUC5AC and MUC1 mucins and MUC1 has been shown to be important in limiting infection by Helicobacter and Campylobacter in a mouse model of infection." (PMID 23056622, 2012). "Mice lacking the Muc1 and Muc5AC mucins have a higher H. pylori density after infection than wild-type mice." (PMID 40667878, 2025). "When the cells were infected with HMPV, MUC5B was more induced in pediatric cells compared to adult cells on day 5 after infection, but no significant changes were observed in the expression of MUC5AC." (PMID 40143308, 2025). "Unlike RV-A1, RV16 induced both, MUC5B and MUC5AC at 24 h post-infection and this was inhibited by ECSN6." (PMID 39538325, 2024). "Compared to sham-infected and placebo-treated groups, RV-A1-infected and ECSN6-treated animals showed increase in Cxcl2 and Cxcl10 at 24 h post infection but not Tnf-α and Muc5ac." (PMID 39538325, 2024).
infection (continued). "The importance of MUC5B, and its role in mucociliary clearance (MCC), was demonstrated in studies of Muc5b knockout mice, where MUC5B, but not MUC5AC, was found to be indispensable for normal airway clearance and infection control in the airways." (PMID 36675209, 2023). "In IAV-exposed tracheobronchial ALI tissues, we observed viral antigen presence within multiple cell types at 24 h post-infection (hpi), with basal cells (KRT5+) being the dominant infected cell type, followed by ciliated cells (α-tubulin+) and goblet cells (MUC5AC+)." (PMID 35962146, 2022). "We found that sputum MUC5AC concentrations correlated positively with sputum neutrophil elastase concentrations, and negatively with the change from baseline in sputum SLPI and elafin concentrations, during infection." (PMID 35239513, 2022). "Compared to RV-A (RV-1B) infection, RV-C (RV-C15) infection induced higher BALF eosinophilia, mRNA expression of IL-5, IL-13, IL-25, Muc5ac and Gob5/Clca, protein production of IL-5, IL-13, IL-25, IL-33 and TSLP, and expansion of ILC2 in naive and HDM-immunized BALB/c mice." (PMID 35386658, 2022). "We observed that MUC5AC induction peaked on day 3 in the time course of these RV-induced COPD exacerbations, preceding airway cellular inflammation, which peaked between days 9 and 15 after infection." (PMID 35239513, 2022). "We observed a significant increase in sputum MUC5AC from baseline in RV-infected COPD patients on day 3 after infection, with no increase observed in healthy control individuals." (PMID 35239513, 2022). "RV-C15 infection increased airway eosinophilic inflammation and mRNA expression of IL-13, Muc5ac and Muc5b in Rorafl/fl mice but not Rorafl/flIl7rCre littermates." (PMID 33968043, 2021). "Goblet cells of the surface epithelium, together with the submucosal glands, produce the major gel-forming mucins MUC5AC and MUC5B, which play a central role in normal host defense against infection via mucociliary clearance and antimicrobial properties of mucus." (PMID 32637364, 2020). "Expression of mucin 5 AC (Muc5AC), a pivotal player for worm expulsion, or defensin alpha 1 (Defa1) was not affected by the infection at this time." (PMID 26377648, 2015). "Mice with chronic schistosomiasis were to a certain extent resistant to strain hvPR8, indicating that the infection with S. mansoni had either induced the production of type I or type III interferons or that other protective mechanisms, like the production of Muc5ac, were active." (PMID 25398130, 2014). "All our infection studies were with HT29-MTX-E12 cells after 21 days of culture because at this time they had formed tight junctions and secreted a mature adherent mucus layer which contained the mucin MUC5AC and trefoil protein TFF1." (PMID 23056622, 2012). "Increased gene expression of MUC1, MUC6 and MUC20 was observed, while MUC5AC did not change during infection." (PMID 21569362, 2011). "Immunofluorescence microscopy, RT-PCR, and tandem mass spectrometry (data not shown) confirmed the de novo expression of Muc5ac after infection in the KO mice." (PMID 20138044, 2010). "During acute infection, however, Muc5ac is not degraded by T. muris E/S derived proteases." (PMID 29355990, 2018). "Mucin-5AC (MUC5AC) is an extracellular matrix structural constituent, which is a gel forming glycoprotein of gastric and respiratory tract epithelial that binds microorganisms that are then removed by the mucocilary system thereby protecting the epithelial cells from infection." (PMID 27880807, 2016). "Moreover, MUC2 and MUC5AC not just as a structural component of the mucus barrier but also act as a crucial effector molecule during infections of the intestine." (PMID 25365201, 2014). "In this work, we observed that only Muc5ac was induced after hMPV infection, but not Muc5b." (PMID 22606349, 2012). "However, following hMPV infection, the absence of IL-12p40 exacerbated Muc5ac expression over 8 times when compared to WT mice." (PMID 22606349, 2012).
infection (continued). "No changes were observed in MUC5AC transcription level during infection." (PMID 21569362, 2011). "Moreover, Muc5ac is up-regulated in the wild-type (WT) mice that are resistant to infection, but not in those unable to expel." (PMID 20138044, 2010). "To assess whether hBAEC infection with Omicron subvariants exert any differential pattern compared to ancestral strain, we evaluated the colocalization of the SARS-CoV-2 nucleocapsid protein with Muc5ac (a goblet cell marker) and ZO-1 (a tight junction marker)." (PMID 40733536, 2025). "Consistent with our observations for SARS-CoV-2, secreted mucins MUC5AC and MUC5B did not protect against infection for most viruses, with the exception of MERS-CoV." (PMID 35879412, 2022). "We observed no significant increase in the ratios from baseline during infection in our experimentally infected individuals with COPD, suggesting a coordinated upregulation of both MUC5AC and MUC5B during RV infection in the individuals with COPD." (PMID 35239513, 2022). "Compared to uninfected cells, HMPV infection induced a significant fold-increase expression of MUC1 (8.3 ± 2), MUC2 (43.4 ± 13), MUC4 (54 ± 12), MUC5ac (23.3 ± 11.5) and MUC19 (77 ± 35), while no significant induction of MUC15, MUC16 and MUC20 was observed." (PMID 32899224, 2020). "While gene expression of Muc5b and Muc5ac was no different between the two genotypes, at any age, we wondered if the epithelial layer of the CFTR-KO had more mucins in storage, prepared for release into the airway in the event of an infection or in response to an airway irritant." (PMID 35574458, 2022).